ALB (albumin)
Diseases named in the same sentence as ALB in open-access papers (continued):
Sharing a sentence is not in itself a finding about the gene and the disease.
chronic kidney disease (continued). "However, the new iteration of the clinical practice guidelines for the identification and classification of chronic kidney disease incorporated urine albumin to creatinine ratio as part of risk stratification." (PMID 25649135, 2015). "Several studies have identified important risk factors for rCDI, including advanced age, chronic renal insufficiency, elevated white blood cell count, low serum albumin, use of proton pump inhibitors (PPI), and continued use of systemic antimicrobials during the initial CDI episode (iCDI)." (PMID 24898123, 2014). "Additionally, studies have shown that low serum albumin is associated with vascular dysfunction, atherosclerosis, and chronic kidney disease, which may share inflammatory pathways with periodontitis." (PMID 41463003, 2025). "The liver is the main site of albumin synthesis; changes in its serum concentration may indicate liver dysfunction, typically indicating chronic damage, while losses are also possible due to renal loss in the context of acute or chronic kidney disease." (PMID 41376020, 2025). "Additionally, tolvaptan has been shown to decrease the incidence of AKI in patients with acute decompensated heart failure and advanced chronic kidney disease.The association between the administration of human blood albumin and the incidence of acute kidney injury is a topic of debate." (PMID 40124680, 2025). "Notably, the bitter sensitive alleles were also nominally associated with chronic kidney diseases and a range of markers of kidney health, including urinary proline betaine levels, glomerular filtration rate, serum non-albumin protein, and glucose levels 2 h after an oral glucose challenge." (PMID 40498099, 2025). "Multiple studies have demonstrated that MASLD is a significant risk factor for chronic kidney disease (CKD) and is closely associated with elevated urinary albumin levels, suggesting a potential link between hepatic and renal metabolic dysfunction." (PMID 40416385, 2025). "Microalbuminemia, characterized by a urinary albumin concentration between 20 and 200 mg/L, is a critical marker in assessing the risk of chronic kidney disease (CKD), diabetic nephropathy, and various other chronic conditions." (PMID 40558473, 2025). "PNI is a measure of combined serum albumin and lymphocyte counts, and patients with low PNI may have low serum albumin, while patients with chronic kidney disease may have low serum albumin due to chronic systemic inflammation or loss of albumin into the urine." (PMID 40070651, 2025). "The results showed that albuminuria severity, as indicated by the urine albumin-to-creatinine ratio, was independently associated with progressive chronic kidney disease (CKD) after both radical and partial nephrectomy." (PMID 39734569, 2024). "Urinary albumin-to-creatinine ratio (uACR) is a well-known marker of glomerular injury and is, therefore, an important diagnostic marker of chronic kidney disease (CKD)." (PMID 36175972, 2022). "Recently, the geriatric nutritional risk index (GNRI) is used to assess serum albumin kinetics and physical condition and has been utilized as a nutritional assessment index in Japanese chronic kidney disease (CKD) patients." (PMID 34772346, 2021). "A GFR of < 60 ml/min/1.73m2 or a urinary albumin-to-creatinine ratio (uACR) of ≥ 30 mg/gCr is independent risk factor for all-cause mortality, cardiovascular mortality, kidney failure, acute kidney injury, and kidney disease progression in chronic kidney disease (CKD)." (PMID 33656638, 2021). "Likewise, in a cross-sectional study of 45 adult chronic renal disease patients and 45 sex- and age-matched controls there was significant reduction in serum total T4, total T3, albumin and total protein levels with an associated increase in TSH levels compared to healthy controls." (PMID 33401560, 2021).
chronic kidney disease (continued). "In addition, inflammation negatively correlated with albumin levels, perhaps due to inflammation-induced proteolysis, agreeing with previous reports that albumin predicts all-cause and cardiovascular mortality in chronic kidney disease patients." (PMID 34571942, 2021). "The introduction of urine albumin to creatinine ratio (ACR) testing during outpatient visits in selected periods after liver transplantation may enable the early identification of patients at risk of developing chronic kidney disease." (PMID 34438524, 2021). "Chronic kidney disease (CKD), low serum albumin, and anemia are known risk factors for cognitive decline in older people." (PMID 33028210, 2020). "Aging; increased blood glucose, serum uric acid and white blood cells; decreased serum pH and albumin; coma; and preexisting chronic kidney disease (CKD) were risk factors of AKI in patients with DKA." (PMID 32050921, 2020). "Chronic kidney disease (CKD) is a type of kidney disease associated with gradual loss of kidney function, decreased glomerular filtration rate or increased albumin excretion in urine." (PMID 32582768, 2020). "The correlation of low serum albumin with mortality in patients with chronic kidney disease (CKD) is partly linked to its association with systemic inflammation." (PMID 29298330, 2018). "Kidney Disease Improving Global Outcomes (KDIGO) 2013 updated the classification and risk stratification of chronic kidney disease (CKD) to include both the level of renal function and urinary albumin excretion (UAE)." (PMID 24990184, 2014). "Multivariate analysis identified age, chronic kidney disease, low albumin, elevated creatinine, CRP, the MLR, and hospital stay as independent mortality predictors." (PMID 41816734, 2026). "Current guidelines recommend use of sodium–glucose cotransporter-2 inhibitors (SGLT2 inhibitors) for kidney protection in people with type 2 diabetes and early-stage chronic kidney disease (CKD) based on a urinary albumin/creatinine ratio (uACR) of ≥3 mg/mmol." (PMID 41206830, 2026). "Microalbuminuria, defined as a urinary albumin concentration between 20 and 200 mg/L, serves as an early marker of kidney damage and a critical predictor of chronic kidney disease (CKD), diabetic nephropathy, and cardiovascular diseases." (PMID 40558473, 2025). "Classical history of DKD was described as an initial rise in urine albumin excretion, then progressive decrease in glomerular filtration rate, and finally end-stage renal disease, which develops several decades after initial diagnosis of DM." (PMID 40576805, 2025). "For example, albumin guanidinylation was detected in patients with chronic renal failure, leading to a conformational change and altered transport properties of albumin." (PMID 40563206, 2025). "The search utilized combinations of the following terms: “antioxidant albumin”, “oxidative stress”, “inflammation”, “preeclampsia”, “vascular endothelial dysfunction”, “renal dysfunction”, and “chronic kidney disease”." (PMID 39857389, 2025). "Univariate analysis showed that cerebrovascular disease, end-stage renal disease, Rutherford category ≥ 4, a low albumin concentration (<3.5 g/dL), and a high NLR were significantly associated with 5-year mortality." (PMID 39797294, 2025). "Chronic kidney disease (CKD) is often diagnosed when the estimated glomerular filtration rate (eGFR) is below 60 mL/min/1.73 m2 or the urine albumin-to-creatinine ratio (UACR) is 30 mg/g or higher, based on KDIGO guidelines." (PMID 40674065, 2025). "Regarding nephropathy, 36 participants (47%) had urinary albumin levels below the threshold, 24 (31%) showed microalbuminuria, 15 (19%) presented with overt proteinuria, and two (3%) had reached chronic renal failure." (PMID 40502874, 2025). "Estimated glomerular filtration rate (eGFR) and serum albumin-to-creatinine ratio (ACR) levels increase with the increasing BMI, suggesting obesity is a risk factor for development of chronic kidney disease (CKD)." (PMID 41299531, 2025).
chronic kidney disease (continued). "Forest-plot analysis showed no significant PNI-subgroup interactions when stratifying by age, sex, acute kidney injury, chronic kidney disease, myocardial infarction, albumin, immunosuppressant, and corticosteroid use (all P-values for interaction > 0.05)." (PMID 40667438, 2025). "We also found a relationship between initial plasma endothelin 1 concentrations and serum albumin concentrations following 1 year (n = 27; p = 0.05; r = −0.4) and 2 years (n = 27; p = 0.05; r = −0.4) of monitoring in the chronic kidney disease cohort." (PMID 41517469, 2025). "The baseline mean estimated glomerular filtration rate (Chronic Kidney Disease Epidemiology Collaboration equation) was 54 ml/min/1.73 m2 (standard deviation 24) and the median urine albumin:creatinine ratio was 293 mg/g (IQR 86–783)." (PMID 41220896, 2025). "Consistently with these observations, there were significantly elevated levels of carbonylated proteins and oxidized human serum albumin (HSA) in the plasma of patients with chronic kidney disease (CKD)." (PMID 40227417, 2025). "Chronic kidney disease (CKD), classified by the cause, an estimated glomerular filtration rate (eGFR) < 60 ml/min/1.73m2 and/or albumin-to-creatinine ratio (ACR) ≥ 3 mg/mmol for a minimum of three months, is a major public health issue." (PMID 40033300, 2025). "A recent publication showed that flies fed a HFD can recapitulate key features of chronic kidney disease, including lipid droplet formation, altered mitochondria dynamics, and endocytosis defects observed as reduced uptake of dextran and albumin." (PMID 41474553, 2025). "Kidney function parameters including estimated glomerular filtration rate (eGFR) and urine albumin excretion are commonly used to diagnose chronic kidney disease (CKD)." (PMID 40004202, 2025). "On the other hand, chronic kidney disease (CKD) is characterized by a persistent rise in urinary albumin excretion (albuminuria), a diminished estimated glomerular filtration rate (eGFR), or other indicators of renal dysfunction." (PMID 40943149, 2025). "The 2012 Kidney Disease: Improving Global Outcomes (KDIGO) Clinical Practice Guideline for the Assessment and Management of Chronic Kidney Disease (CKD) used estimated glomerular filtration rate (eGFR) and urinary albumin-to-creatinine ratio (UACR) as the basis for CKD risk stratification." (PMID 40810070, 2025). "Cirrhosis and chronic kidney disease are known to affect serum albumin and total cholesterol levels independently of nutritional status." (PMID 41517419, 2025). "The determination of urinary albumin, crucial for chronic kidney disease (CKD) diagnosis and monitoring, typically employs quantitative techniques as the gold standard." (PMID 40977823, 2025). "Albuminuria, characterized by the presence of albumin in urine, is a well-recognized marker of kidney damage and is predictive of both chronic kidney disease (CKD) and cardiovascular morbidity and mortality in adults." (PMID 40700436, 2025). "Factors associated with patient fatality or prolonged hospitalization included older age, cancer, chronic kidney disease, higher Charlson and McCabe indices, elevated C-reactive protein, and low albumin concentrations." (PMID 38792341, 2024). "Currently, urinary albumin testing(spot urine sample) is already recommended for all patients with T2D to assess for chronic kidney disease." (PMID 38291519, 2024). "The importance of the ratio of creatinine to urinary protein, albumin, and low-molecular weight protein as a urinary marker in chronic kidney disease patients is widely recognized." (PMID 37676464, 2024). "Previous studies have demonstrated a significant correlation between serum albumin levels, renal function, and anemia in chronic kidney disease patients, aligning with our research findings." (PMID 39621534, 2024). "Chronic kidney disease (CKD) is defined as kidney damage resulting from reduced GFR or increased albumin excretion." (PMID 38307949, 2024).
chronic kidney disease (continued). "Research suggests that individuals with lower serum albumin levels in the diabetic kidney disease population are more prone to progress to end-stage renal disease (ESRD), leading to an unfavorable prognosis." (PMID 38600468, 2024). "Coexisting arrhythmia and chronic kidney disease, lower hemoglobin and albumin values, requiring oxygen therapy, systemic corticosteroids, antibiotics and IMV were associated with lower survival probability of AECOPD patients." (PMID 38898420, 2024). "The concept of displacing protein-bound uremic toxins (PBUTs) from their binding sites on plasma proteins, particularly albumin, offers a novel therapeutic approach in the management of chronic kidney disease (CKD)." (PMID 38592263, 2024). "Guidelines for chronic kidney disease (CKD) or DKD recommend that DKD be diagnosed based on urinary albumin excretion (UAE) and renal function as represented by estimated glomerular filtration rate (eGFR)." (PMID 39152372, 2024). "Follow-up three months after discharge by the renal team revealed persistent high protein in the urine, low serum albumin, and chronic kidney disease stage 3 G3bA3." (PMID 39552984, 2024). "Chronic kidney disease (CKD) is one of the main global causes of morbidity and death, and it is usually diagnosed with kidney function tests, kidney imaging and the albumin-to-creatinine ratio." (PMID 39063457, 2024). "In patients with chronic kidney disease, these modifications are more common and can affect albumin’s transport function." (PMID 38592263, 2024). "Urine protein, serum albumin, and chronic kidney disease stage results at the three-month follow-up." (PMID 39552984, 2024). "In patients with T2DM, DKD was assessed by glomerular filtration rate (< 60 mL/min/1.73 m2 using the Chronic Kidney Disease Epidemiology Collaboration algorithm), proteinuria (urinary albumin to creatinine ratio ≥ 30 mg/g), or both." (PMID 38400938, 2024). "The top six risk factors for DKD progression to chronic kidney disease were hemoglobin, hemoglobin A1c (HbA1c), serum uric acid (SUA), plasma fibrinogen, serum albumin, and neutrophil percentage." (PMID 37308973, 2023). "Chronic kidney disease is defined as an elevated urine albumin excretion (albumin-to-creatinine ratio ≥ 30 mg/g) or reduced glomerular filtration rate (GFR < 60 mL/min/1.73 m2), or both." (PMID 38068310, 2023). "ACR and urinary albumin levels are highly sensitive indicators for early detection of kidney injury in chronic kidney disease (CKD), and can reflect the severity of kidney damage." (PMID 37365530, 2023). "The impact of serum urea-to-albumin ratio has been investigated in critically ill patients with non-chronic kidney diseases, septic shock and community-acquired pneumonia." (PMID 37240644, 2023). "Elevated urinary albumin excretion, also termed albuminuria, is another essential test for the screening and management of chronic kidney disease, particularly in diabetes." (PMID 37545693, 2023). "There are two key markers for chronic kidney disease (CKD): the urine albumin-to-creatinine ratio (UACR) and the estimated glomerular filtration rate (eGFR)." (PMID 37090383, 2023). "In multivariate analyses, albumin (p < 0.001) and chronic kidney disease stage 2 (GFR < 90 mL/min/1.37 m2; p = 0.042) were identified as independent metabolic prognostic markers for survival." (PMID 37297851, 2023). "Increased urinary albumin excretion serves as an indicator not only for early-stage kidney disease but also as an independent predictor for the related risk of cardiovascular events (CV), as well as chronic kidney disease (CKD)." (PMID 37710270, 2023). "Four independent risk predictors were identified and integrated into the nomogram: chronic kidney disease, albumin level, shock, and heart rate." (PMID 37994450, 2023).
chronic kidney disease (continued). "Increased urinary albumin excretion (UAE) and a decrease in glomerular filtration rate (GFR) are associated with DN along with elevated blood pressure and end-stage renal disease (ESRD)." (PMID 37872916, 2023). "The study’s purpose is to explore the link of serum albumin on renal progression in patients with chronic kidney disease (CKD)." (PMID 36922779, 2023). "Chronic kidney disease is characterized by reduced glomerular filtration rates and increased urinary albumin excretions." (PMID 37996949, 2023). "Some studies recently pointed out that in patients with both albuminuria and chronic kidney disease (CKD), the albumin excretion rate (AER) and eGFR are strongly associated with DR." (PMID 36726740, 2023). "Smoking is harmful, and its cessation is recommended to prevent chronic kidney disease, which often begins with abnormal leakage of albumin in the urine, called albuminuria." (PMID 40017893, 2023). "The urinary albumin- and protein-to-creatinine ratios (UACR and UPCR, respectively) are key endpoints in most clinical trials assessing risk of progression of chronic kidney disease (CKD)." (PMID 37174733, 2023). "Lower lymphocyte counts, hemoglobin levels, albumin levels, and higher incidence of chronic kidney disease were found in immunocompromised patients, which is consistent with a previous study." (PMID 36875372, 2023). "This was particularly high in patients with chronic kidney disease, atrial fibrillation, urinary albumin excretion ≥300 mg/g, and stroke." (PMID 38173815, 2023). "Previous studies have demonstrated that nicorandil reduces urinary albumin excretion in models of chronic kidney disease and diabetic kidney disease." (PMID 36454699, 2023). "Current guidelines on chronic kidney diseases (CKD) from the Kidney Disease Improving Global Outcomes (KDIGO) recommend measuring albuminuria to quantify proteinuria since albumin is the predominant protein in the vast majority of proteinuric kidney diseases." (PMID 35204548, 2022). "Chronic kidney disease (CKD) represents a disease entity with a gradual loss of the renal function, which is usually measured by the estimated glomerular filtration rate (eGFR), accompanied by kidney damage (e.g., increased urinary albumin)." (PMID 34997128, 2022). "Focusing on each patient, four of nine patients (patients 1, 4, 5, and 7) in the unsuppressed PRA group had chronic kidney disease (defined as an eGFR less than 60 mL/min/1.73 m2) or a urine albumin-to-creatinine ratio (UACR) > 30 mg/g creatinine." (PMID 35482752, 2022). "Among all the risk factors for mortality of DFUs patients in this study, CCI was ranked first, followed by combined HCE, dementia, osmolality, stroke, serum albumin, chronic kidney disease, HCO3-, hemoglobin and HbA1c." (PMID 36093085, 2022). "Urinary albumin excretion and serum creatinine are the common clinical biomarkers used for diagnosis and staging of renal impairment among chronic kidney disease (CKD) patients." (PMID 36323795, 2022). "Chronic kidney disease (CKD) associates an inflammatory process marked by inflammatory cytokines such as blood MCP-1 and IL-6 and C-reactive protein to albumin ratio in serum." (PMID 35735634, 2022). "Albumin, one of the most mentioned serum proteins in laboratory examination, has long been used to evaluate one’s progression in chronic kidney disease (CKD)." (PMID 35328515, 2022). "The MURAL model comprises 5 parameters: age, presence of atherosclerosis, chronic kidney disease, antiplatelet use, and serum albumin level." (PMID 36482571, 2022). "Future studies measuring albumin in the urine and blood urea nitrogen, creatinine, glomerular filtration rate and creatinine clearance over time are needed to assess chronic renal disease among patients with HIV in SSA." (PMID 35855029, 2022). "Effects of Shenkang injection (SKI) on the levels of Scr, UA, and ALB in serum of chronic renal failure rats*." (PMID 35674582, 2022).